WNT16 (Wnt family member 16)
Diseases named in the same sentence as WNT16 in open-access papers (continued):
Sharing a sentence is not in itself a finding about the gene and the disease.
medulloblastoma (2 papers, 2014 to 2021). A malignant, invasive embryonal neoplasm arising from the cerebellum. "In accord with previous reports, we identified distinct groups of co-expressed genes that were highly enriched for WNT signalling in WNT medulloblastoma, (including DKK1, DKK2, DKK4, WIF1, LEF1 and WNT16)." (PMID 25412507, 2014). "Transcripts contributing significantly to these enrichments encoded WNT16, DKK1 and LEF1 that are specifically over-expressed in WNT medulloblastoma irrespective of developmental control comparison." (PMID 25412507, 2014). "Whilst previous analysis of genetic/epigenetic changes would not have readily identified the genes identified here, some could have been identified solely through subtype-specific overexpression (as was the case for IGF2BP1 and WNT16 in ALL and ATOH1 in medulloblastoma)." (PMID 34230614, 2021).
acute lymphoblastic leukemia (1 paper, 2020). Leukemia with an acute onset, characterized by the presence of lymphoblasts in the bone marrow and the peripheral blood. "Other Wnts such as Wnt4, Wnt5B, Wnt6, Wnt7B, Wnt9A, Wnt10A, Wnt14, and Wnt16 are robustly expressed in CLL B-cells and acute lymphoblastic leukemia (ALL) cells, whereas these can be scarcely detected in normal pre-B cells." (PMID 33126517, 2020).
adenovirus infection (1 paper, 2018). "β-Catenin was activated by Cre adenovirus infection, and both the mRNA expression and protein concentration of WNT16 decreased." (PMID 30518745, 2018).
ankylosing spondylitis (1 paper, 2021). An autoimmune chronic inflammatory disorder characterized by inflammation in the vertebral joints of the spine and sacroiliac joints. "WNT16 is critical for bone homeostasis, but the effect of WNT16 in ankylosing spondylitis (AS) is still unknown." (PMID 34879876, 2021).
bone sarcoma (1 paper, 2015). A sarcoma that arises from the bone. "In contrast, among noncanonical Wnt ligands, the expression of Wnt5a, Wnt5b and Wnt16 was either decreased or lost in bone sarcoma cells; however, Wnt6, Wnt7b, and Wnt11 were remarkably increased in bone sarcoma cells." (PMID 25999350, 2015).
Brain atrophy (1 paper, 2025). Partial or complete wasting (loss) of brain tissue that was once present. "Lifetime brain atrophy is highly heritable (h2SNP = 41%[95%CI = 38–43%]), and the strongest genome-wide association (N = 43,110) implicates WNT16, a gene linked with neurodegenerative diseases." (PMID 40691153, 2025).
cerebrovascular disease (1 paper, 2024). "The genes related to cardiovascular and cerebrovascular disease annotated by the Hippo signaling pathway were Bmp4, Tcf7l2, and Wnt16." (PMID 38195688, 2024).
diabetic (1 paper, 2021). "However, further studies are still required to clarify the role of Wnt16 in the development of diabetes." (PMID 34042263, 2021).
Duchenne muscular dystrophy (1 paper, 2021). Duchenne muscular dystrophy (DMD) is a neuromuscular disease characterized by rapidly progressive muscle weakness and wasting due to degeneration of skeletal, smooth and cardiac muscle. "Variants near CPED1 and WNT16 have been reported to have pleiotropic effects on LM and BMD in the pediatric population, and it has been reported that in Duchenne Muscular Dystrophy patients, up-regulation of CPED1 by muscle-specific microRNAs improved skeletal muscle function." (PMID 33889153, 2021).
hepatocellular carcinoma (1 paper, 2021). A malignant tumor that arises from hepatocytes. "NE activates hematopoietic stem cells and causes them to secrete sFRP1, and sFRP1 collaborates with the Wnt16/B-catenin positive feedback loop to promote hepatocellular carcinoma (HCC) progression." (PMID 34988010, 2021).
Hypertension (1 paper, 2022). The presence of chronic increased pressure in the systemic arterial system. "This may be an alternate mechanism for adipogenesis suppression in APVAT preadipocytes; however, more studies are required to determine if PIEZO1 and Wnt16 activation can promote myofibrogenesis of these cells during hypertension." (PMID 36120469, 2022).
knee osteoarthritis (1 paper, 2024). "Because of the similarities between the inflammatory microenvironment of knee osteoarthritis (KOA) and TMJOA, it is reasonable to introduce Wnt16, which has been shown to be critically important in KOA, in the treatment of TMJOA." (PMID 39248388, 2024).
leiomyoma (1 paper, 2023). A well-circumscribed benign smooth muscle neoplasm characterized by the presence of spindle cells with cigar-shaped nuclei, interlacing fascicles, and a whorled pattern. "Moreover, the expression of WNT16 in leiomyoma stem cells was increased in response to estrogen and progesterone and led to growth of leiomyoma cells in a paracrine manner through activation of canonical WNT signaling." (PMID 36835153, 2023). "This analysis indicated that the expression of WNT16, CACNA1D, DCX, and WIF1 was significantly higher, while the expression of MTMR8 was significantly lower in myometrium adjacent to MED12-mutated leiomyomas compared to myometrium adjacent to MED12 wild-type leiomyomas." (PMID 36835153, 2023). "In addition, the myometrial expression of WNT16 in MED12-mutated specimens was greater compared to myometrium of mutation-negative leiomyomas." (PMID 36835153, 2023). "Here we showed that WNT2, WNT4, and WNT16 are overexpressed in leiomyomas, and that this upregulation was more pronounced in MED12-mutated leiomyomas compared to MED12 mutation-negative specimens, which is in line with previous reports." (PMID 36835153, 2023).
lentivirus infection (1 paper, 2020). Virus diseases caused by the Lentivirus genus. "Besides using shRNA to knock down Wnt16 expression, we used lentivirus infection to overexpress Wnt16 in PDCs to uncover whether up-regulated Wnt16 would promote the early process of osteogenesis." (PMID 33282557, 2020).
myeloma (1 paper, 2010). "The five remaining genes (NRG2, Wnt4, Wnt11, Wnt16 and FGF18) were considered as a "myeloma MGF" although they were not statistically significantly overexpressed in MMC compared to environment cell populations." (PMID 20465808, 2010).
postmenopausal osteoporosis (1 paper, 2019). Metabolic disorder associated with fractures of the femoral neck, vertebrae, and distal forearm. "Specifically, deletion of WNT16 reduces cortical bone thickness and femur strength, with a more severe phenotype in female than in male mice, suggesting that WNT16-based therapy could be effective for postmenopausal osteoporosis." (PMID 31582989, 2019).
progeria (1 paper, 2022). "We also present here the miRNAs and interactomes for the three genes connecting aging, the aging pathway, and progeria: WNT16 (hsa-mir-181a-5p), UCP2 (hsa-mir-26a-5p and hsa-mir-124-3p), and IGFBP2 (hsa-mir-124-3p, hsa-mir-126-3p, and hsa-mir-27b-3p)." (PMID 36289702, 2022). "WNT16 is among the DEGs with rather drastic changes in gene expression, indicating that WNT16 might be of special importance in both progeria and aging." (PMID 36289702, 2022). "Thus, ADAMTS15 might be an interesting research target in progeria and aging-related research, especially as WNT16 is among the only three DEGs that progeria, aging, and the aging pathway have in common." (PMID 36289702, 2022). "Despite progeria being known as premature aging, only three genes of the aging pathway are differentially expressed in nonagenarians and progeria patients compared to the same group of healthy children: WNT16, UCP2, and IGFBP2." (PMID 36289702, 2022).
prostate tumor (1 paper, 2016). "The WNT16 gene is known to be regulated by NFκB after DNA damage and subsequently activates the canonical Wnt program in prostate tumor cells." (PMID 27078000, 2016).
psoriasis (1 paper, 2019). An autoimmune condition characterized by red, well-delineated plaques with silvery scales that are usually on the extensor surfaces and scalp. "In this study, we also analyzed SNPs in WNT7B, WNT10B, WNT16 and TFC7L2 to investigate a possible association with psoriasis." (PMID 31089877, 2019). "In the light of these results, it is tempting to assign WNT16 a key role in epidermal hyperproliferation but more studies are needed to determine if WNT16 is involved in the pathogenesis of psoriasis." (PMID 31089877, 2019). "Associations between single nucleotide polymorphisms for WNT7B, WNT10B, WNT16 and TCF7L2 genes and psoriasis were tested." (PMID 31089877, 2019). "The functional contribution of WNT signaling to the pathophysiology of psoriasis needs to be studied further, but it can be speculated that WNT7B, WNT10B, TCF7L2 and WNT16 contribute to the pathogenesis of psoriasis." (PMID 31089877, 2019). "A more intense expression of WNT16 was observed in lesional skin from patients with psoriasis compared to healthy control subjects and non-lesional skin." (PMID 31089877, 2019). "Levels of WNT7B, WNT10B, WNT16 and TCF7L2 gene expression in peripheral blood samples of patients with psoriasis were not significantly different compared to healthy individuals." (PMID 31089877, 2019). "The aim of this study was to describe the expression of WNT7B, WNT10B, WNT16 and TCF7L2 in lesional and non-lesional skin and in whole blood of patients with psoriasis compared to healthy individuals and to investigate if SNPs in these genes can be correlated to psoriasis." (PMID 31089877, 2019).
rheumatoid arthritis (1 paper, 2024). A chronic, systemic autoimmune disorder characterized by inflammation in the synovial membranes and articular surfaces. "Genetic predispositions—such as the involvement of HLA-DR4 in rheumatoid arthritis and WNT16 in cortical bone thickness —may contribute to asymmetric joint damage and bone density reduction." (PMID 39768575, 2024).
scoliosis (1 paper, 2024). A congenital or acquired spinal deformity characterized by lateral curvature of the spine. "First, a larger sample cohort including wider spectrum of scoliosis severity is warranted to validate the interaction between WNT16 SNPs and Vit-D-related SNPs on the benefits of vitamin D supplementation for future clinical use." (PMID 38275421, 2024). "Further investigations with a larger sample size and wider spectrum of scoliosis severity are required to validate our findings regarding the interaction between WNT16 and Vit-D status in patients with AIS." (PMID 38275421, 2024).
spontaneous abortion (1 paper, 2025). Expulsion of the product of FERTILIZATION before completing the term of GESTATION and without deliberate interference. "In this study, we delineated the expression profile of WNT16 in DSCs and uncovered its differential expression patterns between normal pregnancies (NP) and recurrent spontaneous abortion (RSA) patients." (PMID 41438735, 2025). "Endometrial stromal cells (ESCs) from non-pregnant women and decidual stromal cells (DSCs) from normal pregnancies (NP) and recurrent spontaneous abortion (RSA) were accessed for WNT16 expression by RT-qPCR, ELISA and immunohistochemistry." (PMID 41438735, 2025).
uveitis (1 paper, 2018). An inflammatory process affecting a part of or the entire uvea. "A homolog of WNT16, WNT3 (ENSP00000225512) was also predicted to participate in uveitis-specific pathogenesis." (PMID 30349554, 2018). "According to recent publications, our inferred genes (WNT2, WNT16, WNT3, WNT7A, and WNT7B) are functionally related to the initiation and progression of uveitis due to their interference to the proliferation of urea and mixed immune cells." (PMID 30349554, 2018). "For its specific contribution on the pathogenic approach of uveitis, no direct evidence confirmed that WNT16 participates in uveitis-specific pathogenesis." (PMID 30349554, 2018). "However, two recent studies confirmed that WNT16, together with MNT5, participate in the pathogenesis of uveitis by interfering immune responses." (PMID 30349554, 2018). "Therefore, speculating that WNT16 and WNT3 may be functionally related to uveitis is reasonable." (PMID 30349554, 2018).
cancer (20 papers, 2012 to 2025). A tumor composed of atypical neoplastic, often pleomorphic cells that invade other tissues. "Wnt Family Member 16(WNT16) is a WNT family member protein closely associated with the development of chemoresistance in cancer cells." (PMID 36550571, 2022). "We used Sanger sequencing to orthogonally validate the presence of WNT16 hotspot mutations in BRAF mutant cancers (n = 79) and identified frameshift mutations in 20.2% (16/79) of cancers." (PMID 32384699, 2020). "WNT16 is a competitive inhibitor of canonical WNT and the mutation of WNT16 is common in BRAF mutant cancers." (PMID 32384699, 2020). "Clinicopathological analyses of WNT16 mutant cancers revealed an association with MSI (mutant: 100% vs. Wt: 61.9%, p = 0.0054), right sided tumors (mutant: 100% vs. Wt: 86.8%, p = 0.038) and earlier stage at diagnosis (Mutant: 87.6% vs. Wt: 63.2%, p = 0.029)." (PMID 32384699, 2020). "Moreover, the WNT16 pathway has been associated with treatment-induced damage to the tumor microenvironment, promoting cancer therapy resistance, senescence reversal, and cellular transformation." (PMID 39062630, 2024). "In cancer, the loss of WNT16 may facilitate excessive canonical WNT activation by failure to compete with more potent WNT ligands, such as WNT3A and WNT8." (PMID 32384699, 2020). "This novel strategy shows that targeting CAF-derived factors like Wnt16 can overcome drug resistance and improve cancer treatments." (PMID 40124335, 2025). "Wnt16 downregulation resensitized cancer cells to cisplatin, remodeled the TME and fibroblast populations, and inhibited angiogenesis." (PMID 40124335, 2025). "Immunohistochemical scores for the NF‐κB downstream target gene WNT16 followed a similar pattern: cisplatin increased WNT16 (P = 6.2 × 10−6 vs. the cancer‐positive group) and the combination therapy reduced it (P = 0.0001 cisplatin vs. cisplatin plus DMAPT)." (PMID 37533407, 2023). "These gene sets contain several genes that have been widely studied in the context of cancer, including WNT16, CEBPD and EGFR." (PMID 37381036, 2023). "In combination with data indicating poorer prognosis for patients harboring WNT16 mutant cancers, it is likely that WNT16 acts as a tumor suppressor." (PMID 32384699, 2020). "As a result, HGF, platelet derived growth factor A and WNT16, reported to be produced by CAFs from other cancer types, are also expressed in GCAFs, which correlate with the poor overall survival." (PMID 30038550, 2018). "Moreover, WNT16 and GNG12 were implicated as potential cancer drivers (p = 0.06 and p = 0.0006, respectively)." (PMID 32384699, 2020). "When corrected for covariates that may influence cancer stage (MSI, tumour side, sex, age, CIMP), WNT16 mutations were marginally associated with an earlier stage at diagnosis (p = 0.05)." (PMID 32384699, 2020). "Cancers that lack WNT16 are prone to excessive ligand-dependent WNT activation (p16) and may represent a subset of patients that could benefit from this therapy." (PMID 32384699, 2020). "WNT16 was also identified as a potential cancer driver gene." (PMID 32384699, 2020). "In early stage recurrence, the significant pathway associated genes upregulated were MMPs and genes associated with cancer cell adhesion/motility including CDC42, RAC1 while a significant upregulation of WP genes including Wnt4 and Wnt16 was noted during stage IIIc recurrence." (PMID 27902969, 2017). "In addition to WNT5A, WNT16 and WNT2B also produce alternative transcripts that are differentially expressed in human tissues and cancers." (PMID 24260410, 2013). "Simultaneously, the downregulation of WNT16, cell cycle regulators such as SLC7A5, and histone genes, like HIST2H3A and HIST1H2BJ, points to disruptions in the Wnt signaling and chromatin remodeling, processes central to cancer cell proliferation and epigenetic regulation." (PMID 40756515, 2025).
cancer (continued). "Cancer and organismal injuries were the top two diseases and function categories that were predicted to increase, along with neurological (HAND2), hepatic system (APOE, CACNG4, CAMK2B), respiratory system (WNT16), and skeletal muscle developmental disorders (ADD2, HAND2)." (PMID 39508990, 2025).
tumor (14 papers, 2017 to 2025). "This innovative system leverages quercetin’s ability to downregulate Wnt16 and P-glycoprotein expression, thereby modifying the tumor microenvironment and reversing multidrug resistance (MDR) to bolster DOX’s effectiveness." (PMID 40458787, 2025). "For instance, quercetin can suppress Wnt16 expression, thereby decreasing tumor cell resistance to chemotherapeutic agents and helping to remodel the tumor matrix." (PMID 40978482, 2025). "In detail, quercetin plays a pivotal role in reducing Wnt16 and P-gp levels, further facilitating tumor microenvironment remodeling and MDR reversal to enhance DOX’s functionality." (PMID 40458787, 2025). "Previous studies have shown that WNT16 signaling in fibroblasts induces EMT functions in tumor cells and promotes their resistance to chemo- and radiotherapy through autocrine and paracrine signaling." (PMID 39062630, 2024). "The NPs significantly decreased Wnt16 expression and re-sensitized tumor cells to cisplatin in stroma-enriched bladder cancer." (PMID 36297426, 2022). "Expression levels the remaining Wnt ligands, including Wnt1, Wnt3, Wnt4, Wnt5A, Wnt8A, Wnt9B, Wnt10A and Wnt16, remained insignificantly different between liver tumors tissues and adjacent non-tumor tissues." (PMID 30814912, 2019). "For example, radiation-induced WNT16 expression from tumor stroma was shown to promote tumor cell survival, resulting in attenuated effects of cytotoxic chemotherapy." (PMID 29088840, 2017). "Comparative transcriptome analysis revealed significantly increased WNT16 signaling in H2A.J OE fibroblasts after IR exposure, promoting the fundamental mechanisms of tumor development and progression, including the activation of the epithelial–mesenchymal transition." (PMID 39062630, 2024). "It is also possible that residual GA-loaded nanoparticles may accumulate around tumor vessels and be absorbed more efficiently by TAFs, which regulate the secretion of Wnt16, an essential damage response program (DRP) molecule, around tumor vessels." (PMID 37496657, 2023). "These NPs could downregulate Wnt16 to elicit several advantages, such as re-sensitizing tumor cells to cisplatinum, reprogramming the TME, as well as inhibiting angiogenesis." (PMID 36297426, 2022). "These include MEN1, a known WNT pathway tumor suppressor, and WNT16, a WNT ligand that may act as an antagonist of ligand mediated WNT activation." (PMID 32384699, 2020). "WNT16 is a member of the WNT family and is concerned in tumour cell growth and survival via activation of β‐catenin." (PMID 36847709, 2023). "In the “tumor only” setting, the most differentially upregulated genes in EVP were related to its paracrine function such as Gdf6, a member of the TGFβa agonist, Wnt16, epiregulin, and neuroregulin." (PMID 30604758, 2019). "WNT16 is a WNT ligand, a seemingly unlikely candidate tumor suppressor." (PMID 32384699, 2020). "Wnt16 downregulation was also obtained with LCP NP loaded with the prodrug quercetin, demonstrating its capability to downregulate Wnt16 levels, reduce the number of CAF, normalize the collagen content in tumor tissue and improve nanoparticles delivery into the tumor." (PMID 30871158, 2019).
infection (1 paper, 2022). The state of being infected such as from the introduction of a foreign agent such as serum, vaccine, antigenic substance or organism. "As one of the Wnt family members, Wnt16 is involved in the immune response to pathogen infection." (PMID 36713173, 2022).